SNORA54 (small nucleolar RNA, H/ACA box 54)
Synonyms: ACA54
Gene: Small nucleolar RNA gene on chromosome 11 (2,963,771 to 2,963,893, reverse strand). Ensembl gene ENSG00000207008.
Gene Ontology:
Biological process: RNA processing
Cellular component: nucleolus
Homologues: Orthologues: chimpanzee SNORA54 (100% identical), macaque SNORA54 (98% identical), mouse Gm23297 (88% identical), rat Snora54 (88% identical).
Diseases named in the same sentence as SNORA54 in open-access papers:
SNORA54 is named in the same sentence as 3 diseases in open-access papers, as found by Europe PMC text mining. Sharing a sentence is not in itself a finding about the gene and the disease.
SNORA54 shares sentences with these, for which no sentence is quoted: alcohol dependence (1 paper); ischemic stroke (1); Stroke (1).